IL10 (interleukin 10)
Diseases named in the same sentence as IL10 in open-access papers (continued):
Sharing a sentence is not in itself a finding about the gene and the disease.
COVID-19 (continued). "Moreover, age, BMI, fever duration, leucocyte count, lymphocyte proportion, proportion of CD3+ T cells, tumor necrosis factor α (TNF-α), and IL-10 were confirmed to be independently associated with severe H1N1 infection in post-COVID-19 era." (PMID 38566022, 2024). "In addition, interleukin-10, like interferons, is a cytokine whose overexpression is associated with inflammation and immunity as well as with the progression of COVID-19." (PMID 38980578, 2024). "TNF-α-GA and AA genotypes and A allele, IL-8 TA and AA genotypes and A allele and CXCR-2 CC and CT genotypes have significant associations with mortality risk in COVID-19 patients, while GA and GG genotypes of the IL-10 are shown to confer significant protection against mortality from COVID-19." (PMID 38544825, 2024). "Additionally, the protected animals also exhibited a significant down-regulation in the RNA levels of other important inflammatory mediators such as Il-6 and Il-10, which have been associated with COVID-19 disease progression and severity." (PMID 39087555, 2024). "Many studies have identified the association between severe COVID-19 and heightened platelet activation as well as deficient interferon (IFN)-α levels have been also associated with increased interleukin (IL)-10 expression in patients progressing to severe or life-threatening COVID-19 conditions." (PMID 39329758, 2024). "In IL10 rs1800872 TT genotype (P < 0.0001, OR 3.39, 95% CI 2.65–4.35) and GG in rs1800896 (P < 0.0001, OR 2.65, 95% CI 2.04–3.45) were correlated to a higher risk of COVID-19 mortality." (PMID 36882862, 2023). "It seems that IL-10 is involved in the up-regulation of inflammatory reactions in COVID-19 and might be implicated in a cytokine storm." (PMID 37283736, 2023). "This study aimed to assess if the IL10 gene polymorphisms rs1800871, rs1800872, and rs1800896 were linked to coronavirus disease 19 (COVID-19) mortality in different severe acute respiratory syndrome coronavirus 2 (SARS-CoV-2) variants in the Iranian population." (PMID 36882862, 2023). "The COVID-19 mortality rate was associated with IL10 rs1800872 TT genotype in the Alpha (OR 2.06, 95% CI 1.42–2.98) and Omicron BA.4 (OR 10.81, 95% CI 6.73–17.36) variants and GT in the Alpha (OR 1.44, 95% CI 1.10–1.89) and Delta (OR 2.97, 95% CI 2.19–4.02) variants." (PMID 36882862, 2023). "Association of polymorphisms of IL10 rs1800872 gene with D-dimer response and severity of COVID-19." (PMID 37390087, 2023). "However, a study in the literature showed that compared to other diseases that cause cytokine-releasing syndromes, IL-10 levels in COVID-19 are lower." (PMID 37239991, 2023). "Noteworthy, increased serum levels of IL-10 are associated with COVID-19 severity." (PMID 37523305, 2023). "Our study demonstrates a probable association of IL10 rs1800872 gene polymorphism with the severity of COVID-19, as well as a strong relationship between IL10 rs1800872 gene polymorphism and D-dimer in Kazakh populations with severe COVID-19." (PMID 37390087, 2023). "A similar elevation in IL-10 was reported in pneumonia caused by influenza viruses and COVID-19." (PMID 37876022, 2023). "High levels of cytokines, such as IL-2, IL-1b, and IL-10, may be associated with thrombotic complications in patients with COVID-19." (PMID 37112918, 2023). "In COVID-19, a higher level of IL-10 was found to be associated with a more severe disease." (PMID 37969879, 2023). "Increases in levels of KP metabolites, including anthranillic acid and 3-hydroxykynurenine associated with high IL-10/8 and immunosuppression in COVID-19 patients, further support the possible role of KP metabolites as potential prognostic biomarkers of COVID-19." (PMID 36991597, 2023). "Association of IL10 rs1800872 gene polymorphisms with the severity of COVID-19." (PMID 37390087, 2023).
COVID-19 (continued). "This evidence further supports an involvement of inflammatory process in COVID-19-associated chemosensory dysfunction and suggests a role for IL-10 as reliable predictor of OD/GD course as well as potential pharmacological strategy to reach a successful recovery in post-COVID-19 patients." (PMID 37359549, 2023). "The significantly increased levels of the most relevant cytokines modulating the inflammatory processes, such as IL-6 and IL-10, further support the notion that increased systemic inflammatory conditions are associated with poorer COVID-19 outcomes, especially in the setting of geriatric patients." (PMID 36522763, 2022). "Cytokine dysregulation (particularly transforming growth factor-β (TGF-β), Tumor Necrosis Factor (TNF)-α, Interleukin (IL)-1β, Interferon (IFN)-γ, IL-6, and IL-10) are known to be associated with psychiatric disorders, and have been shown to be elevated in patients with COVID-19." (PMID 35053059, 2022). "IL-10 SNPs have been also associated with severity and outcomes in patients with COVID-19." (PMID 36233516, 2022). "Since the IL6/IL10 ratio has been demonstrated as a sensitive biomarker of COVID-19 outcome, aging PLHTLV-1 might be at increased risk of developing severe or critical COVID-19." (PMID 36482436, 2022). "It has been shown that IL-10 and IL-12 (P70) levels predict the risk of COVID-19 progression in hypertensive patients; in s similar manner, these cytokines could be used as biomarkers for behavioral and molecular changes driven by neuroinflammation." (PMID 36362993, 2022). "However, in COVID-19, IL-10 is associated with severe cases and mortality because the cytokine storm intensifies." (PMID 35572964, 2022). "IL-6 and TNF-α may be the most critical factors causing CS; IL-6 and IL-10 levels can be used as a primary index for predicting COVID-19 outcomes." (PMID 36278166, 2022). "This association of IL-10 with poor outcomes in COVID-19 patients might be at least partly explained by secondary infections." (PMID 36275812, 2022). "Moreover, high serum levels of cytokines, such as IL-6, CCL2, CXCL8, CXCL10, IL-2, and IL-10 were associated with COVID-19-related encephalopathy and showed an enhanced systemic inflammatory response." (PMID 36232655, 2022). "There may be a connection between loss of CD45RA+ Tregs and increased levels of IL-10 in severe COVID-19 patients, which may result in increasing mortality rates in these patients." (PMID 36034704, 2022). "Loss of CD45RA+ Tregs and elevated levels of IL-10 have been observed in severe COVID-19 patients, which may lead to hyperimmunity and high mortality." (PMID 35615369, 2022). "Importantly, ACE2 surface translocation was positively associated with hyperactivation and IL-10 and PD-L1 expression in myeloid cells from COVID-19 patients." (PMID 36085197, 2022). "Therefore, post-COVID-19 patients should also benefit from the anti-inflammatory effects of supervised exercise, which is still associated with increased IL-4, IL-10, and decreased chemokines levels." (PMID 36685603, 2022). "Thus, correlations were performed in the current investigation, implying that plasma levels of CRP, SAA, IL-6, CXCL10, VCAM-1, and IL-10, among the linked, exhibit a significant and beneficial association with COVID-19 patient progression." (PMID 35958594, 2022). "Interestingly, beside the pro-inflammatory cytokines and chemokines, IL-10 was significantly associated with COVID-19 status." (PMID 36148228, 2022). "This study was thus carried out to determine the association of rs1800896 and rs1800872 genetic polymorphism in IL-10 gene since we hypothesize that these polymorphisms might play an important role in determining COVID-19 severity." (PMID 37521849, 2022).
COVID-19 (continued). "(2021) identified a likely risk of developing prolonged symptoms of COVID-19 in hospitalized patients, noting that convalescent patients had a lower frequency of IL-10+ CD4+ T cells, IL-17+ CD4+ T cells, and IL-6+ B cells, compared to individuals with acute COVID-19." (PMID 35846757, 2022). "In this sense, other cytokines and chemokines such as MCP-1, IL-10, IL-15, CXCL10, and CCL2 have been associated with SARS-CoV-2 viremia." (PMID 35783606, 2022). "In addition, IL-10 seems to be associated with a milder COVID-19 phenotype exclusively in women, since the highest concentrations of IL-10 were described in women moderately affected by the disease but not in men with the same phenotype." (PMID 35897265, 2022). "We consecutively included patients during the first peak of the COVID-19 epidemic in Brazil and analyzed the expressions of genes encoding interleukin (IL)-1β, IL-6, IL-8, IL-10, IL-12A, IL-12B, and tumor necrosis factor-α in peripheral blood mononuclear cells." (PMID 33819170, 2021). "Although further confirmatory studies are required, inducing IL-10 upregulation could be clinically relevant in COVID-19-associated acute respiratory distress syndrome (ARDS) and vasculitis, by reinforcing ACE2 levels." (PMID 34646263, 2021). "Indeed, in line with our findings, it has been shown that IL10 and IL1ra are significantly associated with COVID-19 severity and poor outcomes." (PMID 33767713, 2021). "IL-6 >142.5 pg/mL, IL-10 >10.8 pg/mL, IL1β > 4.68 pg/mL, sIL-2rα >804.5 pg/mL, IL-1Ra >88.4 pg/mL, and IL-18 > 144 pg/mL values were associated with the development of critical COVID-19 in the age-adjusted univariate analysis." (PMID 34422145, 2021). "Multivariate analyses showed that higher levels of IL-6, IL-8, and IL-10 remained significantly correlated with shorter survival time and that the amount of Ts cells was negatively associated with the possibility of death in COVID-19 patients." (PMID 33542929, 2021). "Notably, we observed significantly elevated IL10 expression in the seropositive, symptomatic patients, a cytokine whose elevated expression has been associated with COVID-19 disease severity." (PMID 33608566, 2021). "Altogether, our data suggest that high levels of circulating IL-6, TNF, and IL-10 might be associated with the severity of COVID-19, while only an increased level of IL-6 might be related to the severity of SARS and MERS." (PMID 34046036, 2021). "Reduced IL-6 and IL-10 levels were found in 95% and 19% of patients, respectively, suggesting that COVID-19 may have a role in cellular immune deficiency." (PMID 34122618, 2021). "Furthermore, IL-10 amplifies viral sepsis-related hyperinflammation in critically ill and severe COVID-19 patients and is linked to T-cell exhaustion, presumably through overactivation and proliferation." (PMID 34539631, 2021). "It remains unknown whether G-MDSCs produce IL-10 during COVID-19 and whether the increased production of IL-10 observed during severe disease is a cause or a consequence." (PMID 34473802, 2021). "In addition, the airway epithelial cells of healthy individuals produce IL-10; however, the epithelial cells of COVID-19 patients are deficient in the production of IL-10." (PMID 33806624, 2021). "In pediatric COVID-19 reports, increasing levels of serum interleukin (IL)-6 and IL-10 are also associated with greater COVID-19 disease severity, although the levels of these cyto- kines are not significantly different between infected children with and without elevated serum liver enzymes." (PMID 33777864, 2021). "Interestingly, we observed that sVCAM-1 was highly correlated with GM-CSF, the TH1 chemokine CXCL10 and IL-10, which our team and others recently identified as the peculiar “cytokine/chemokine signature” associated with poorer outcome in COVID-19 patients." (PMID 34422854, 2021).
COVID-19 (continued). "Interestingly, a recent study reported that IL-10 and IL-1RA levels are associated with disease severity in COVID-19 patients using longitudinal blood samples." (PMID 33986193, 2021). "Accordingly, recent data on the ratio of the pro-inflammatory cytokine IL-6 and the anti-inflammatory cytokine IL-10 suggested that serum cytokines may be used for risk stratification in hospitalized COVID-19 patients." (PMID 34540715, 2021). "We found modest increases in the Th17-type immune response–associated biomarkers IL-17 and IL-23 in COVID-19 patients and a more significant increase in IL-10 levels in all severity groups, with the highest concentrations observed in patients who succumbed to COVID-19, as previously reported." (PMID 33232303, 2021). "The loss of CD45RA+ Tregs and increase in the IL-10 levels may lead to hyperimmunity in severe COVID-19 patients, possibly associated with high mortality among these patients." (PMID 34631206, 2021). "These immunoregulatory effects have been mainly associated with its ability to induce anti-inflammatory cytokines such as IL-10 or regulatory T cells and therefore, the suppression of pro-inflammatory cytokines, which are associated with the severe course of COVID-19." (PMID 34501583, 2021). "Collective data indicate that anti-inflammatory cytokines, including IL-10, are likely produced to limit the cytokine storm observed following SARS-CoV-2 infection; however, IL-10 fails to achieve this, as high levels of IL-6 in conjunction with IL-10 are associated with severe cases of COVID-19." (PMID 34251989, 2021). "While, as detected in the plasma of our own cohort of patients, increased serum levels of IL-10 have been widely associated with COVID-19 and disease severity (reviewed in37), several factors may explain these results." (PMID 34021148, 2021). "TNF, IL-10, and IL-8 are associated with the severity of COVID-19." (PMID 34046036, 2021). "We further found that elevated and a trend of a continued increase in cytokine levels, including IL-2R, IL-6, IL-8, IL-10 and TNFα, and decreased lymphocyte subsets, especially helper T cells, suppressor T cells and NK cells, were associated with a poor prognosis of COVID-19." (PMID 33365277, 2020). "Moreover, COVID-19 monocytes exhibited a similar profile as monocytes from patients with hepatitis C, in which upregulation of PD-L1 and IL-10, and downregulation of HLA-DR and CD86 were the hallmark of the infection." (PMID 33003471, 2020). "Moreover, higher levels of IFNγ TNFα, IL-2, and IL-10 have been associated with COVID-19 severity, further supporting a pathogenic role." (PMID 33634100, 2020). "However, the severe COVID-19 cases showed an increase in IL-6, IL-2R, IL-10, and TNFα secretion associated with a severe decrease in T cells, particularly CD4+ T cells." (PMID 32793246, 2020). "And our results supported the idea that IL-10 may be a risk factor for COVID-19." (PMID 40101060, 2025). "This study significantly advances our understanding of COVID-19 severity by evaluating a comprehensive panel of cytokines and clinical markers, confirming the robust association between elevated levels of IL-1β, IL-6, IL-8, IL-10, IL-17A, IL-23, TNF-α, and IFN-α with critical disease outcomes." (PMID 39861879, 2025). "Three polymorphisms; the IL-10; the − 592 C > A (rs1800872) and IL-10 -1082 A > G (rs1800896) and the TNFa; -308 G > A (rs1800629) were found to correlate with susceptibility and clinical progress of different viral infections and as predictors for severity and mortality in patients with COVID-19." (PMID 38287362, 2024). "Also, some of the biosignatures including but not limited to TNF, IL10, have been verified using multiplex biosensor techniques to be associated with COVID-19, and as such these biosignatures could serve as markers to monitor the disease development." (PMID 39040605, 2024).
COVID-19 (continued). "Furthermore, this study identified that age, BMI, fever duration, leucocyte count, lymphocyte proportion, proportion of CD3+ T cells, TNF-α, and IL-10 were independently associated with occurrence of severe cases in children hospitalized with H1N1 infection during the post-COVID-19 period." (PMID 38566022, 2024). "In men over 35 years of age, Coronavirus Disease 2019 (COVID-19) led to increased sperm DNA fragmentation, a decrease in the total antioxidant capacity, and an elevation in the levels of interleukin-1β and interleukin-10." (PMID 37958725, 2023). "Elevated levels of IL-6, IL-8, and IL-10 were associated with the disease severity of COVID-19, and elevated levels of IL-1β, IL-6, and IL-8 were related to the prognosis of COVID-19 patients, which could be used to evaluate COVID-19 patients' disease severity and prognosis." (PMID 35540724, 2022). "Notably, elevated IL-10 levels are associated with a poor prognosis of patients with COVID-19." (PMID 35337004, 2022). "Thus, IL-10 upregulation may be clinically relevant in acute respiratory distress syndrome and vasculitis associated with COVID-19." (PMID 35631030, 2022). "However, when analyzed according to the time from disease onset, the IL-6 elevation was found only at the late stage of severe COVID-19 while IL-10 and IL-1RA levels were significantly associated with disease severity and patients’ outcomes already at the first week after symptom onset." (PMID 35887283, 2022). "However, a marked early increase in the level of the proinflammatory cytokine IL-10 may be associated with COVID-19 severity." (PMID 35369061, 2022). "We identified key cytokines that were consistently associated with severity, like IL-10, an enhancer of NK cytotoxicity, and IL-15, a stimulator of NK cells, Obviously, the modeling methodology can be used to identify key players and predict outcome in new variants of COVID-19." (PMID 35529862, 2022). "Taken together, levels of IL-6, IL-8, and IL-10 were associated with the disease severity of COVID-19, and levels of IL-1β, IL-6, and IL-8 were correlated with the prognosis of COVID-19 patients, which may be used to predict the disease severity of COVID-19." (PMID 35540724, 2022). "Similarly, IL-10 concentration is elevated in severe COVID-19 cases and may be associated with the depression observed in T-cell counts." (PMID 35572964, 2022). "Thus, monitoring the levels of multiple cytokines, especially IL-6, IL-8, and IL-10, during the early stages of COVID-19 may help to identify patients who have the greatest risk for development of ARDS." (PMID 34088317, 2021). "Direct correlations between COVID-19 outcomes and individual cytokines and immune cell populations indicate symptoms of COVID-19 are associated with elevations in interleukin 1 beta (IL-1β), IL-6, interleukin 10 (IL-10), and TNFα), as well as a general lymphopenia." (PMID 33967944, 2021). "Our findings suggest that discharged patients continue to recover from the physiological effects of COVID-19, and the association of IL-4, IL-6, and IL-10 levels with metabolic changes and liver function repair may have important implications for clinical manifestations and treatment of COVID-19." (PMID 34307393, 2021). "This was accompanied by an increased trend of systemic IL-10 and IL-6, as well as a dysregulated serum lipid response dominated by polyunsaturated fatty acid-containing phosphatidylethanolamine, recapitulating cytokine and lipid responses associated with severe human COVID-19." (PMID 34159329, 2021). "In conclusion, ferritin, D-dimer, CRP, NLR, cytokines (IL-6, IL-18, and IL-10), and cytokine receptors (IL-1Ra and sIL-2rα [sCD25]) in combination with clinical information may aid the early identification of patients at risk of critical COVID-19." (PMID 34422145, 2021).